VIM (vimentin)
Diseases named in the same sentence as VIM in open-access papers (continued):
Sharing a sentence is not in itself a finding about the gene and the disease.
astrocytoma (14 papers, 2010 to 2025). "In the present study, we demonstrated that EV71 infection caused the rearrangement of vimentin in human astrocytoma cells." (PMID 24073199, 2013). "The transition from lower- to higher-grade astrocytomas is often accompanied by an increase in vimentin expression, further supporting its role as a marker of tumor progression." (PMID 40937216, 2025). "Both Olig2 and GFAP can be expressed in astrocytomas and oligodendrogliomas, whereas vimentin is more strongly expressed in astrocytomas." (PMID 40362055, 2025). "High HIP1R and low vimentin levels were observed in oligodendroglioma compared to low HIP1R and high vimentin levels in astrocytoma." (PMID 36425564, 2022). "At the mRNA level it is significantly prognostic in GBM and even more so in astrocytoma where the distribution of vimentin expression appears much broader than in GBM." (PMID 30987208, 2019). "Two cytoskeletal proteins, HIP1R and vimentin, were identified as relevant markers that could distinguish between oligodendroglioma and astrocytoma." (PMID 36425564, 2022). "Given that identifying 1p/19q status is needed to distinguish between IDH mutant astrocytoma and oligodendroglioma, and the high cost of genetic testing needed to identify it, the HIP1R/vimentin/ATRX approach could serve as an easy and reliable surrogate in clinical practice." (PMID 36425564, 2022). "Although vimentin protein has been found to be disorganized in the astrocytoma cells treated by high dose of OA, it has not been determined whether its expression level was also affected in the same conditions." (PMID 23991044, 2013).
brain tumor (14 papers, 2005 to 2023). "Like the unmodified forms, the citrullinated peptide fragment of GFAP and vimentin therefore appeared to be associated with pediatric brain tumors with a lower degree of aggressiveness, according to the WHO classification." (PMID 37761239, 2023). "Brain tumors, on the other hand, express proteins that are characteristic for developing brains, including vimentin." (PMID 33187334, 2020). "Vimentin expression and migration also played a important role in brain tumor cell survival and development." (PMID 29746255, 2018). "When taken together, these results indicate that vimentin is both a marker of brain tumor pathogenesis and a predictor of chemotherapy resistance." (PMID 25162558, 2014). "Within brain tumors in particular, vimentin expression also correlates with temozolomide resistance, a frontline therapy for the treatment of GBM." (PMID 25162558, 2014). "The protein Vimentin was observed to be overexpressed in all the three brain tumor tissue samples." (PMID 34055594, 2021). "In a second step we looked for the expression by SON vessels of nestin or vimentin, two intermediate filament proteins that are expressed by the endothelial cells constituting newly formed capillary vessels in the developing CNS or in brain tumors." (PMID 15790414, 2005). "The C6 cell line originated from a chemically induced rat brain tumor and expresses GFAP and vimentin, which is a property of undifferentiated astrocytic cell type." (PMID 22174936, 2011). "Vimentin and GFAP citrullination is produced by the PAD2 enzyme, and the identification of citrullinated peptides of these proteins in less aggressive histotypes of pediatric brain tumors would suggest a potential role in clinical prognostic applications." (PMID 37761239, 2023). "We found that CAIX and vimentin (VIM) (Mes2 meta-module) were highly expressed in GBM brain tumor compared to non-tumor tissue, due in part to their increase in pseudopalisading regions." (PMID 34059134, 2021).
chordoma (14 papers, 2013 to 2025). Chordomas are rare malignant tumors arising from embryonic remnants of the notochord in axial skeleton. "ARF-8 cells also expressed 10 different keratins, as well as 6 different S100A proteins, along with high quantities of vimentin, all classes of proteins that are also associated with chordoma diagnosis." (PMID 39684443, 2024). "In addition, these samples were identified based on immunohistochemistry (IHC), staining for diagnostic biomarkers of chordoma including cytokeratin, vimentin, EMA, S-100, and brachyury." (PMID 28978123, 2017). "Immunohistochemistry revealed that the chordoma was positive for the S100 protein, vimentin, epithelial membrane antigen, and cytokeratins." (PMID 39731799, 2025). "A reduction in the additional chordoma markers vimentin and pan-cytokeratin was observed by immunocytochemistry, but not as prominent as for brachyury." (PMID 40332566, 2025). "Neoplastic chondrocytes express vimentin and S-100, while chondroid chordoma shows strong immunoreactivity for brachyury, cytokeratin, and epithelial membrane antigen (EMA)." (PMID 35484609, 2022). "To illuminate the mechanism of the suppressive roles of CMTM3 in chordomas, we detected the expression of the epithelial specific junction protein E-cadherin and the mesenchymal proteins N-cadherin and Vimentin in CMTM3-overexpressed JHC7 and U-CH1 cells and CMTM3 silenced MUG-Chor1 and U-CH1 cells." (PMID 34560882, 2021). "Both chordoma and chondrosarcoma may be positive for S-100 and vimentin." (PMID 36291287, 2022). "Knockdown of Smad3 suppressed the migration and invasion of chordoma cells and was accompanied by the upregulation of E-cadherin and downregulation of N-cadherin and vimentin, which indicated that Smad3 may be involved in the metastasis of late-stage chordoma by promoting EMT." (PMID 29880900, 2018). "Compared with other clusters, which were considered putative malignant clusters, putative nonmalignant clusters were checked for lower gene expression levels of chordoma tumor cell markers (TBXT, S100A1, and VIM) according to the published literature 12,18,19." (PMID 36127333, 2022). "Chondromas are reported to be positive for vimentin and S-100 protein and chordomas for CK, EMA, S-100 protein, vimentin and brachyury; these are pathological discrimination indexes between these two types of tumors." (PMID 35692788, 2022).
Ewing sarcoma (14 papers, 2009 to 2026). A small round cell tumor that lacks morphologic, immunohistochemical, and electron microscopic evidence of neuroectodermal differentiation. "CD99 positivity is seen in both MC and Ewing’s sarcoma, along with vimentin, CK, NKX2.2, FLI1, and CD99." (PMID 40585664, 2025). "GlyTR1 target expression in cell-surface vimentin-positive (CSV+) Ewing sarcoma cells was significantly greater than in TNBC (clone 11) cells, and >95% were killed by GlyTR1 in the ALI organoid despite the terminally exhausted TILs." (PMID 41005308, 2025). "Imaging and biopsy investigations revealed a small, vimentin positive, round blue cell tumour suggestive of Ewing’s sarcoma compressing the brainstem." (PMID 29540190, 2018). "Immunohistochemical analysis of Ewing’s sarcoma typically reveals the expression of vimentin and MIC2, as was observed in the present case." (PMID 25663869, 2015). "Imunohistochemistry based studies on EMT markers in earlier studies have shown that Ewing’s sarcoma cells are positive for Vimentin." (PMID 23145994, 2012). "Ewing sarcoma is positive for vimentin and CD99 but lacks chondroid areas." (PMID 39503009, 2024). "Immunohistochemistry was positive for vimentin, NKX2.2, CD99, and synaptophysin, confirming the diagnosis of Ewing sarcoma." (PMID 42281714, 2026). "For example, another article reported a case of Ewing sarcoma of the scapula that was positive for CD99, vimentin, and bcl-2." (PMID 39588414, 2024). "Diagnosis of Ewing sarcoma should be based on positive immunohistochemical reactions for vimentin (+++) and CD99 (+++) and negative reaction for desmin, actin, ML, and CD10, associated as in our experience with a high (90%) proliferative index Ki67." (PMID 25960901, 2015).
glaucoma (14 papers, 2013 to 2025). Increased pressure in the eyeball due to obstruction of the outflow of aqueous humor. "Vimentin was significantly greater in the ONH in glaucoma, with higher signal intensity (~ 195% of control on average) and area occupied (~ 200% of control on average) up to 1.5 mm along the ONH." (PMID 35986368, 2022). "β2-agAAbs are one of several autoantibody species (e.g. anti-HSP70, anti-vimentin) that have been detected in AH of patients with glaucoma." (PMID 34025634, 2021). "Previous studies found that vimentin is a cell identity marker of TM cells and glaucoma development is followed with vimentin hydrolysis." (PMID 31680442, 2020). "To investigate druggability of vimentin, we exploited rabbit Tenon's capsule fibroblast (RbTCF) cell cultures and the rabbit glaucoma filtration surgical (GFS) model of fibrosis." (PMID 23667686, 2013). "In glaucoma, α-smooth muscle actin and vimentin are altered and can be induced by TGFβ." (PMID 38223904, 2023). "Because myopia is associated with differentiation of myofibroblasts that are characterized with vimentin, it is plausible that VMAC contributes to the pathogenesis of glaucoma via myopia." (PMID 40149693, 2025). "Intense GFAP and vimentin staining was observed across the retina and ONH in both controls and glaucoma." (PMID 35986368, 2022). "Furthermore, differential AAB reactivity against vimentin (VIM), another intermediate filament, was found in serum samples from glaucoma patients compared with healthy subjects." (PMID 34943212, 2021). "The only difference between the two models was that vimentin was increased in glaucoma but showed no change after nerve crush." (PMID 23826199, 2013). "Furthermore, some previous identified glaucoma autoantigens including heat shock protein 60 dDA (HSPD1), heat shock protein 70 kDa (HSPA1B), vimentin (VIM), α-enolase (ENO1) and superoxide dismutase 1 (SOD1) could be detected." (PMID 30899261, 2019).
ischemia (14 papers, 2011 to 2023). A hypoperfusion of the BLOOD through an organ or tissue caused by a PATHOLOGIC CONSTRICTION or obstruction of its BLOOD VESSELS, or an absence of BLOOD CIRCULATION. "Of these, various proteins have been previously linked to ischemia, including clusterin, vimentin, and vitronectin." (PMID 37175625, 2023). "EMT causes fibrosis by filling the tubular interstitial with fibrotic substances such as vimentin and α-smooth muscle actin, causing arterial ischemia and atrophy of glomeruli and kidney tubules." (PMID 33679720, 2020). "Here we used a mouse model of genetically attenuated reactive gliosis (mice deficient for IF proteins GFAP and vimentin) to determine the impact of ischemia-induced reactive gliosis on the regenerative capacity of transplanted human iPSC-derived NSPCs." (PMID 29401502, 2018). "Downregulation of Human growth and transformation-dependent protein (HGTD-P), a protein which is proapoptotic in ischemia, and downregulation of Vimentin, which has been shown to mediate microglial activation, supports the beneficial function of tmTNF." (PMID 31440125, 2019). "When retinas are subjected to ischemia and preadministrated with vehicle, enhanced vimentin/GFAP immunoreactivity was found to be present simultaneously with the reduction in b-wave amplitude." (PMID 28709426, 2017). "Astrocyte IFs, including vimentin, are critical structures for cellular stress responses because astrocytes are sensitive to stress exposure, including osmotic and mechanical stresses resulting from ischemia, trauma, and brain edema." (PMID 36393840, 2022). "As a result of ischemia, astrocytes release vimentin, nestin, IL-1β, monocyte chemotactic protein-1, and glial fibrillary acidic protein, which contribute to the development of reactive gliosis and the formation of glial scars after ischemia." (PMID 33922467, 2021). "In addition, GFAP/Vimentin double-knockout mice showed reduced cortical blood flow in the brain and greater lesions following local ischemia." (PMID 33922467, 2021). "Vimentin and GFAP are intermediate filaments involved in neural plasticity and regeneration and play important roles in responses to stress such as injury, ischemia and neurodegeneration." (PMID 33504361, 2021). "Vimentin and GFAP are both intermediate filaments and are well known to be upregulated in Müller cells and astrocytes in general in the CNS as a response to stress, for instance, ischemia." (PMID 37175625, 2023). "This increase of contractility may exacerbate retinal damage after ischemia, as seen by the increase of GFAP and vimentin along with decreased retinal function 72 hours post ischemia." (PMID 27322388, 2016). "The expression of GFAP, GLAST or vimentin together with a passive current pattern and dye-coupling in a large subpopulation of EGFP+ cells evidenced that polydendrocytes can give rise to reactive astrocytes after ischemia." (PMID 22590616, 2012).
head and neck cancer (13 papers, 2012 to 2025). A primary or metastatic malignant neoplasm affecting the head and neck. "Immunohistochemistry revealed tumor cell nests stained with pan-cytokeratin, that are surrounded by fibroblasts stained with vimentin and build functional units in head and neck cancer." (PMID 31297730, 2019). "The study thus revealed that BN-modulated vimentin expression enhanced the progression of head and neck carcinoma." (PMID 22912735, 2012). "Furthermore, in addition to cytokeratin, our cell cultures were positive for vimentin, a marker of a poor prognosis in head and neck cancer." (PMID 34115931, 2021). "Furthermore, EPCAM knockdown in esophageal and head and neck carcinoma cells resulted in an increase in their migratory capacity following Vimentin expression." (PMID 34680248, 2021). "Upon treatment with BNE, head and neck carcinoma cells showed an increase of vimentin." (PMID 22912735, 2012). "Previously, we have shown that downregulation of vimentin in HN12 cells, a head and neck cancer cell line derived from a metastatic tumor deposit, induces keratin promoter activity and enhances keratin expression." (PMID 36552797, 2022). "By contrast, the proneural marker SOX2 was downregulated, consistent with previous publication in head and neck cancer on the inverse relationship between SOX2 and vimentin." (PMID 30967630, 2019). "To investigate the relationships between EMT, CSCs and TRAF6 in head and neck cancer, we discovered that the expression of TRAF6 in SCCHN was significantly correlated with EMT markers (i.e. Vimentin and Slug) and CSC markers (i.e. CD44, KLF4, ALDH1 and SOX2)." (PMID 29193723, 2018). "Indeed, using recombinant human IL-8 as a treatment of head and neck cancer cells, their Western blot analyses revealed a decrease in the expression of E-cadherin and an increase in the expression of MMP2, MMP9, and vimentin compared to the untreated conditions." (PMID 37628994, 2023).
pancreatic ductal adenocarcinoma (13 papers, 2011 to 2026). An infiltrating adenocarcinoma that arises from the epithelial cells of the pancreas. "We have very recently reported that procollagen 11A1+ cancer-associated stromal cells of pancreatic ductal adenocarcinoma co-express αSMA, and/or vimentin, and/or desmin in different proportions." (PMID 25417197, 2014). "Subsequently, AGR2 downregulation was determined by immunohistochemical staining and correlated with vimentin expression and reduced expression of membranous E-cadherin in pancreatic precursor neoplastic lesions, as well as pancreatic ductal adenocarcinomas." (PMID 28810836, 2017). "The aim of this study was to determine the extent and prognostic significance of vimentin expression in pancreatic ductal adenocarcinomas." (PMID 21448168, 2011). "In conclusion, the results of our study suggest that de novo tumour epithelial expression of vimentin in pancreatic ductal adenocarcinoma is an independent predictor of adverse postsurgical outcome." (PMID 21448168, 2011). "In this study, we investigated vimentin expression in a large series of pancreatic ductal adenocarcinomas treated by surgery and assessed its relationship to survival." (PMID 21448168, 2011). "Vimentin expression was detected by immunohistochemistry on tissue microarrays of surgically resected pancreatic ductal adenocarcinomas from 387 patients." (PMID 21448168, 2011). "Furthermore, vimentin expression was a potential independent adverse prognostic molecular biomarker in patients with pancreatic ductal adenocarcinoma." (PMID 34395245, 2021). "Vimentin expression by the neoplastic cells was observed in 154 (45%) pancreatic ductal adenocarcinomas, and included a wide variation in the extent of cancer cell expression varying from 1 to 95%, with the median percentage of vimentin-labelled cancer cells being 1%." (PMID 21448168, 2011). "In pancreatic ductal adenocarcinoma (PDAC), cell-surface vimentin is a biomarker for isolating CTCs 29-32." (PMID 34659539, 2021). "In addition, WA was reported to exhibit antiangiogenesis activity by binding to the intermediate filaments vimentin and F-actin, as well as nestin, another filament protein that regulates the TGF-β1-induced epithelial–mesenchymal transition in pancreatic ductal adenocarcinoma." (PMID 31319622, 2019).